ENSG00000277444
Gene: Miscellaneous RNA gene on chromosome 2 (144,521,039 to 144,521,116, forward strand). Ensembl gene ENSG00000277444.
Gene Ontology:
Biological process: positive regulation of gene expression
Homologues: Orthologues: mouse Gm56477 (85% identical).